OBI1 (ORC ubiquitin ligase 1)
Description:
E3 ubiquitin ligase essential for DNA replication origin activation during S phase. Acts as a replication origin selector which selects the origins to be fired and catalyzes the multi-mono-ubiquitination of a subset of chromatin-bound ORC3 and ORC5 during S-phase.
Synonyms: C13orf7; RNF219; FLJ13449
Tractability: PROTAC: UniProt records ubiquitination sites on it; ubiquitination databases record sites on it.
Gene: Protein-coding gene on chromosome 13 (78,614,283 to 78,659,166, reverse strand). Ensembl gene ENSG00000152193.
Subcellular location: Chromosome
Subcellular location (Human Protein Atlas): Nuclear bodies; Nucleoplasm; Cytosol
Pathways (Reactome):
Cell Cycle: Cyclin A/B1/B2 associated events during G2/M transition
Gene Ontology:
Molecular function: chromatin binding; protein binding; ubiquitin protein ligase activity; ubiquitin-protein transferase activity
Biological process: protein autoubiquitination; protein monoubiquitination; regulation of DNA replication
Cellular component: chromatin; chromosome; nucleoplasm
Genetic constraint (gnomAD): Loss-of-function variants: 51 observed, 54.96 expected, observed/expected ratio (o/e) 0.93, 90% interval 0.74 to 1.17. The upper end of that interval is the gene's LOEUF score, 1.17, which puts it in group 5 of 6, group 1 being the genes least tolerant of losing a copy. Missense variants: 801 observed, 801.32 expected, observed/expected ratio (o/e) 1, 90% interval 0.94 to 1.06. Synonymous variants: 279 observed, 284.21 expected, observed/expected ratio (o/e) 0.98, 90% interval 0.89 to 1.08.
Homologues: Orthologues: chimpanzee OBI1 (99% identical), macaque OBI1 (97% identical), dog OBI1 (92% identical), rabbit OBI1 (91% identical), pig OBI1 (90% identical), guinea pig OBI1 (89% identical), mouse Obi1 (81% identical), rat Obi1 (80% identical), tropical clawed frog obi1 (34% identical).
Diseases named in the same sentence as OBI1 in open-access papers:
OBI1 is named in the same sentence as 20 diseases in open-access papers, as found by Europe PMC text mining. Sharing a sentence is not in itself a finding about the gene and the disease. The quoted sentences say what the papers report.
colorectal adenocarcinoma (1 paper, 2019). The most common type of colorectal carcinoma. "OBI1 was overexpressed in different tumours, particularly colorectal adenocarcinoma." (PMID 31160578, 2019).
diabetes (1 paper, 2025). "These regions spanned genes (e.g., CCDC42, GYPE, MAP3K20, and OBI1) related to diseases (e.g., malaria infection and diabetes) with differing prevalence and incidence between populations." (PMID 41224710, 2025).
tumor (4 papers, 2019 to 2026). "While HUWE1, UBR5, PRPF19, ARIH2 and OBI1 are mainly related to tumor suppression, DNA damage response and DNA replication, TRIM21 is involved in regulating host innate immunity and viral immune evasion." (PMID 38932241, 2024).
OBI1 also shares sentences with these, for which no sentence is quoted: cancer (4 papers); prostate carcinoma (2); Alzheimer disease (1); Anxiety (1); benign prostatic hyperplasia (1); bone tumor (1); Brain atrophy (1); breast carcinoma (1); colon adenocarcinoma (1); dementia (1); demyelinating disease (1); hepatocellular carcinoma (1); melanoma (1); Mild Cognitive Impairment (1); Prostate Tumor (1); skin cutaneous melanoma (1); uterine corpus endometrial carcinoma (1).